IL13 (interleukin 13)
Diseases named in the same sentence as IL13 in open-access papers (continued):
Sharing a sentence is not in itself a finding about the gene and the disease.
asthma (continued). "Anti-inflammatory activity of GMP in experimental asthma and atopic dermatitis has also been associated with decreased levels of IL-5 and IL-13 in affected tissues." (PMID 32992996, 2020). "The main cells associated with type 2- (T2-) high 2 asthma are eosinophils, due to the participation in the formation of various inflammatory mediators: IL-13, IL-5, chemokines, and cysteinyl leukotrienes, which are the powerful bronchoconstrictors." (PMID 32395125, 2020). "The inflammation caused by asthma is originated from Th2 lymphocytes, which secrete a group of cytokines including IL-5, IL-4, IL-3, IL-13 and GM-CSF." (PMID 32489374, 2020). "A recent study investigated the association of 236 candidate gene polymorphisms and asthma disease severity, and found only one marker, the rs848 in the IL‐13 gene region, significantly associating with symptom severity in adults with asthma." (PMID 33133517, 2020). "IL-13 is a type 2 cytokine that is strongly associated with asthma and induces asthmatic airway remodeling, including increased subepithelial fibroblast proliferation." (PMID 32117962, 2020). "Eosinophils, sources of IL‐4 and IL‐13, have been implicated in tissue remodeling in other diseases including eosinophilic oesophagitis, asthma, and hypereosinophilic syndrome." (PMID 32567222, 2020). "The ILC2 are important sources of IL-13 and have been linked to asthma, an obstructive lung pathology." (PMID 32764367, 2020). "Treatment of the hBSMCs with interleukin-13 (IL-13), an asthma-related cytokine, caused both an upregulation of CD38 protein and a downregulation of miR-140-3p." (PMID 33121100, 2020). "Nonetheless, despite these limitations, we have shown for the first time enrichments both for asthma-associated genes among IL-13 and/or IL-17A responsive genes in ASMCs and for GWAS variants associated with childhood-onset asthma among ASMC QTLs." (PMID 32690065, 2020). "Eosinophilia during asthma development is associated with pro-inflammatory cytokines such as IL-4, IL-5 and IL-13." (PMID 31991647, 2020). "These biomarkers are all continuous in nature and are either associated with IL-13 activation or with previous successful treatment of asthma with a biologic therapy." (PMID 31315668, 2019). "Eos asthma is known to be associated with the Th2 pathway and IL4, IL5, and IL13 are involved in “Th2-high” asthma." (PMID 30941157, 2019). "Recently, three meta-analyses of IL-13 polymorphisms in adults and children suggested that the IL-13+1923 C/T polymorphism is associated with increased risk of asthma." (PMID 31866859, 2019). "Discovered DMRs annotated to genes implicated in allergic asthma, Th2 activation and eosinophilia (EPX, IL4, IL13) and genes previously associated with asthma and IgE in EWAS of blood (ACOT7, SLC25A25)." (PMID 31300640, 2019). "Aberrant production of the Th2 and Th17 cytokines, IL-4, IL-5, IL-13, and IL-17, mediate the induction of the IgE isotype switch, which has long been associated with the pathogenesis of asthma." (PMID 30873032, 2019). "Subgroup analysis showed patients with high periostin level (>50 ng/ml) had a lower risk of asthma exacerbation after receiving anti-IL-13 treatment (MD = -0.30, 95%CI: -0.41–0.19, P<0.001)." (PMID 30703143, 2019). "IL-13 variants were found to interact with household carpet use on the risk of asthma in Taiwanese children." (PMID 31921716, 2019). "In a murine model of asthma, MaR1 reduced both IL-5 and IL-13 expression in iLC2 and this was associated with an increased TGF-beta-dependent generation of regulatory T cells (Tregs) and Tregs-mediated suppression of iLC2." (PMID 30979024, 2019). "Subgroup analysis showed patients with high periostin level had a lower risk of asthma exacerbation after receiving anti-IL-13 treatment." (PMID 30703143, 2019).
asthma (continued). "AAL(S) was shown to reduce the severity in asthma mice models by suppressing inflammation, mucus-secreting cell numbers, type 2-associated cytokines (IL-33, IL-5 and IL-13), serum IgE and airway hyper-responsiveness." (PMID 31623614, 2019). "Asthma is a T helper type 2 (Th2) cell-mediated eosinophilic inflammatory disease, and Th2 cytokines IL-4, IL-5, and IL-13 have been implicated in asthma pathology." (PMID 31852931, 2019). "Conversely, respiratory Chlamydia infection in early life was shown to reduce IL-13Rα2 expression and attenuate IL-13 production with potential secondary benefit later in life on asthma susceptibility." (PMID 30759882, 2019). "Compared to the placebo, anti-IL-13 treatments were associated with significant improvement in asthma exacerbation, FEV1 and AQLQ scores, and reduction in rescue medication use." (PMID 30703143, 2019). "Relatively recent study has reported a single nucleotide polymorphism rs848 in the IL13 gene region that was significantly associated with asthma severity in patients that were lifetime physician-diagnosed as asthmatic in Italy." (PMID 30038057, 2018). "This myofibroblast marker is overexpressed in asthma, and its deficiency in animal models of asthma was shown to attenuate airway inflammation and, in particular, eosinophilia, IL-5 and IL-13 levels in BALF." (PMID 30101406, 2018). "A recent study looked at the impact of variations in IL-13 gene has on asthma phenotypes (variants of asthma disease with different characteristics) in a group of 3577 Taiwanese children." (PMID 29360764, 2018). "For example, an analysis of BAL-derived exosomal miRNAs in asthma reveals the altered expression of 24 miRNAs in asthmatic patients compared to healthy subjects which are implicated in the regulation of IL-13-mediated functions." (PMID 29854739, 2018). "Interleukin-13 (IL-13) is an important Type 2 T helper (Th2) cytokine, controlling biological functions in epithelium and has been linked to asthma, atopic dermatitis and ulcerative colitis (UC)." (PMID 29438285, 2018). "Several types of CD4+ T-cells have been implicated in asthma regulation, including Th2, regulatory T, and Natural killer (NK) T cells producing interleukin (IL)-4 and IL-13." (PMID 29422039, 2018). "As a major finding of these projects, asthma onset has been associated with a number of genes coding for HLA, IL-13, IL-33, thymic stromal lymphopoietin [TSLP], IL-1 receptor-like 1 [IL-1RL1], ST2, and the receptor for IL-33." (PMID 29992143, 2018). "Presumably, interleukins, including IL-4 and IL-13, are strongly associated with inflammatory reactions in asthma." (PMID 30101406, 2018). "TH2 cells mainly secrete the cytokines IL-4, IL-5, and IL-13 to mediate inflammatory and remodeling changes in the airway mucosa that predispose an individual to asthma and to asthma exacerbations." (PMID 29951106, 2018). "IL-13 is associated with various important events during the effector phase of asthma including airway hyper-responsiveness, mucus hyper-production, and airway remodeling." (PMID 29507584, 2018). "Recent evidence indicates that Th2 cytokines (such as IL-5 and IL-13) and other T-cell associated cytokines (such as IL-22 and IL-17A) are involved in allergic airway inflammation in asthma." (PMID 29922162, 2018). "A study conducted on severe asthma in Italian patients found a significant association between the SNP rs848 within the IL-13 gene and severe asthma symptoms." (PMID 29992143, 2018). "In severe asthma, IL-13 has been known as an inflammatory mediator causing bronchial contraction and hypersecretion, bronchial hyperresponsiveness, and asthma severity." (PMID 30210646, 2018). "The pathological features of asthma are thought to be a consequence of the activation of Th2 cells and their associated cytokines including IL-4, IL-5, IL-9, and IL-13." (PMID 29922162, 2018).
asthma (continued). "Most patients with asthma have an eosinophilic infiltration of the airways, associated with increased production of type 2 cytokines including IL-4, IL-5, IL-13 secreted by Th2 cells, together with allergic comorbidities." (PMID 30105031, 2018). "Asthma is generally associated with Th2 cells, which produce a panel of cytokines (IL-4, IL-5, IL-13) that act in synergy to drive lung inflammatory responses, mucus secretion, IgE production, and fibrosis, causing the characteristic symptoms of asthma." (PMID 30105031, 2018). "Uteroglobin/CC10 deficiency caused asthma-like airway inflammation, together with eosinophil-dominance and high expression of type 2 cytokines, including IL-4 and IL-13." (PMID 29642409, 2018). "T2-associated asthma is characterized by the release of interleukins IL-13 and IL-5, promoting eosinophilic infiltration, pro-inflammatory loops, epithelial cell proliferation, goblet-cell metaplasia, and ciliary beating alterations." (PMID 28303134, 2017). "Human asthma is associated with increased basal IL-4 and IL-13 levels in the airway, and segmental airway challenge with allergen induced IL-4 and IL-13 responses." (PMID 29182669, 2017). "Mutations in several type 2 immunity factors, including the major cytokine IL13 as well as eosinophil granule proteins have been linked to severe asthma, suggesting that genetic variation in the allergic immune response can impact disease susceptibility." (PMID 28854632, 2017). "Our result identified that IL-13 +1923C/T variant correlated with increased risk of asthma in both children and adult groups under each genetic model." (PMID 28057889, 2017). "Normal HBECs exposed to the asthma-associated T-helper 2 cell (Th2) cytokine IL-13 showed similar decreases in BPIFA1 levels." (PMID 28165446, 2017). "In our model of chemical-induced asthma, we have previously established a role for T- and B-lymphocytes, with the associated release of both Th1- and Th2-cytokines, including IL-13." (PMID 28704401, 2017). "IL-13 rs20541 and rs1800925 were risk factors for asthma and rs1800925 was significantly associated with total serum IgE levels." (PMID 28057889, 2017). "SNP rs848 in the IL-13 gene region was significantly associated with a continuous measure of symptom severity in adult subjects with severe asthma." (PMID 28057889, 2017). "This is perhaps best illustrated in the case of IL13, where we observe repeated amino acid substitutions in a discrete site across primates linked to asthma susceptibility and increased inflammatory signaling in humans." (PMID 28854632, 2017). "Mixed responses characterized by IL-5 and IL-17 upregulation were associated with Difficult-to-Control disease while IL-4 and IL-13 were associated with Easy-to-Control asthma." (PMID 28686637, 2017). "CXCL-1, IL-5, IL-8, and IL-17A were positively associated with Difficult-to-Control asthma, while IL-4 and IL-13 were positively associated with Easy-to-Control asthma." (PMID 28686637, 2017). "In particular, mutations in IL13 detected in related primates have known molecular phenotypes associated with enhanced immune signaling and asthma susceptibility in humans." (PMID 28854632, 2017). "In conclusion, our results suggested that IL-13 +1923C/T polymorphism was a risk factor for asthma susceptibility, especially in Asians and Caucasians." (PMID 28057889, 2017). "Autophagy is modulated by cytokines, and the cytokine interleukin (IL)-13, which is associated with autophagy, plays an important role in asthma by regulating IgE synthesis, mucus hypersecretion, airway hyper-responsiveness and fibrosis." (PMID 28796252, 2017). "The purpose of the present study was to estimate the relationship between IL-13 +1923C/T polymorphism and asthma susceptibility." (PMID 28057889, 2017). "Overall, our results found that IL-13 +1923C/T polymorphism was significantly associated with increased risk of asthma under each genetic model (P<0.00001)." (PMID 28057889, 2017).
asthma (continued). "Our results found that IL-13 +1923C/T polymorphism was significantly associated with increased risk of asthma under each genetic model." (PMID 28057889, 2017). "Several studies have identified the role of IL-13 +1923C/T polymorphism in asthma susceptibility; however, the results obtained from different geographical populations were very different." (PMID 28057889, 2017). "But a recent study showed that B7-H3 deficient mice developed severe OVA-induced asthma with characteristic infiltrations of eosinophils in the lung, increased IL-5 and IL-13 in lavage fluid, which suggests B7-H3 has a coinhibitory function on Th2 responses." (PMID 28094276, 2017). "We have previously shown that T-cell receptor stimulation of BAL cells causes IL-13 production that is less sensitive to corticosteroids in asthma patients compared to controls." (PMID 27716212, 2016). "Recently, we found that maternal serum and breast milk whey levels of IL-5 and IL-13 are risk markers for asthma-like symptoms among children; whereas whey IgA and TGF-β1 were protective by diminishing the relative risk of asthma-like symptoms." (PMID 27222655, 2016). "In asthmatic patients, allergen challenge initiates the influx of TH2 cells in the airways leading to an increased production of TH2-associated cytokines including IL-4, IL-5, and IL-13 which promote the detrimental inflammation associated with asthma." (PMID 27378934, 2016). "Asthma is a prevalent disease of chronic inflammation in which the Th2 cytokines IL-4, IL-5, and IL-13 are all tightly linked to the pathogenesis of asthma." (PMID 27547445, 2016). "Th2-type cytokines (such as IL-4, IL-5, and IL-13) and chemokine (eotaxin) have been implicated in the promotion of allergic responses in asthma." (PMID 27741312, 2016). "After adjusting for multiple testing and potential confounders, SNP rs848 in the IL13 gene region is significantly associated with a continuous measure of symptom severity in adult subjects with ever asthma." (PMID 26986948, 2016). "Nevertheless as described, this model demonstrates the hallmarks of airway inflammation associated with human asthma, employing the critical processes driven by both the cytokines IL-4 and IL-13." (PMID 26740570, 2016). "Th2 cells are the central players in allergic asthma, as they are major producers of the type 2 cytokines interleukin-4 (IL-4), IL-5, and IL-13, which are all tightly linked to the pathogenesis of asthma." (PMID 26965110, 2016). "MMP1, MMP3, MMP8, and MMP12 levels were associated with severe asthma and were correlated positively with sputum IL-5 levels but negatively with IL-13 levels." (PMID 26851968, 2016). "Th2 cells produce high level of IL-4, IL-5 and IL-13 which are closely associated with asthma symptoms." (PMID 27870920, 2016). "Like rs20541, IL13 rs1800925 has been extensively associated with atopic disease, including asthma, psoriatic arthritis and eczema, as well as with allergy and IgE levels." (PMID 27708669, 2016). "In children, the two IL13 polymorphisms are associated with an increased risk of wheezing and both SNPs interact with household carpet use on late-onset asthma." (PMID 26986948, 2016). "For example, among youth with asthma, more chronic family and household stress is associated with increased production of the Th2 cytokines IL-5 and IL-13, and higher eosinophil counts." (PMID 27965775, 2016). "Th2-type cytokines IL-4, IL-5, and IL-13 have been implicated in promoting allergic responses in asthma." (PMID 26110056, 2015). "The association between IL-13 and IgE productions in asthma suggests that ethanol extracts of Pf suppressed IL-13 secretion and thus tended to reduce IgE production." (PMID 26064160, 2015). "The majority of children who produced IL‐5 (in classes 4 and 5) had accompanying high‐level expression of IL‐13 (relative to Class 3), and high levels of IL‐5 were associated with high prevalence of asthma, wheeze and mite sensitization (classes 4 and 5)." (PMID 26061524, 2015).
asthma (continued). "Our data further support earlier findings that TH2high asthma, as characterized by increased IL-13 production, is more likely to be associated with glucocorticoid responsiveness." (PMID 25772594, 2015). "IL-13 as IL-4 are more involved in allergic inflammation and are increase in experimental model of asthma and IL-13 is strongly associated to mucus production be epithelial cells." (PMID 25816137, 2015). "Airway epithelium differentiation and IL-13 signalling are both implicated in the structural and functional changes associated with asthma." (PMID 25848896, 2015). "Although IL-13 is implicated in asthma pathogenesis, its production is strongly inhibited by glucocorticoids; indeed, the TH2high asthma phenotype is now widely regarded as a marker of glucocorticoid responsiveness." (PMID 25772594, 2015). "Asthma is a chronic inflammatory disease of the airways characterized by increased presence of eosinophils and production of Th2 cytokines, such as IL-13, that causes bronchial hyperreactivity and goblet cell metaplasia." (PMID 24453940, 2014). "We have shown significant univariate associations between HDM-specific IL-5 and IL-13 responses at age 3 years, 5 years and 8 years and the presence of asthma and atopy at 8 years." (PMID 24875149, 2014). "From age 3 years HDM-specific IL-5 and IL-13 responses were associated with atopy and asthma at the age of 8 years." (PMID 24875149, 2014). "Among the Th2 cytokines, IL-4 and IL-13 are investigated the therapeutic intervention in asthma and other Th2-associated diseases." (PMID 24936861, 2014). "In a IL-13-driven model of experimental allergic asthma, GGTenu1 mutant mice were protected against asthma, despite the presence of cellular glutathione deficiency and oxidant stress in lung airway epithelial cells." (PMID 25132819, 2014). "Associations between interleukin-13 (IL-13) polymorphisms and asthma risk remained controversial and ambiguous." (PMID 23437086, 2013). "Many epidemiological studies also revealed that the variants in the IL-13 gene were associated with total IgE level, increased eosinophil count, atopy and asthma among children." (PMID 23382814, 2013). "Consistent with previous well-known knowledge, we found the significant genetic association in IL-13 gene, and wheeze is a good predictor for development of asthma in children." (PMID 23382814, 2013). "Evidence suggests that asthma is caused by a Th2 immune response and that some Th2 cytokines, such as IL-13, are involved in the regulation of muc5ac production in asthmatic models." (PMID 24349268, 2013). "Results from the cumulative meta-analyses showed a trend of more obvious association between IL-13 +1923C/T polymorphism and an increased risk of asthma as information accumulated by year." (PMID 23841068, 2013). "The aims of our study are to evaluate the effects of IL-13 genetic variants on asthma phenotypes, and explore the potential interaction between IL-13 and household environmental exposures among Taiwanese children." (PMID 23382814, 2013). "This meta-analysis, including a total of 13698 cases and 38209 controls, examined the association between the IL-13 +1923C/T polymorphism and asthma risk." (PMID 23841068, 2013). "So far, a lot of studies investigated the association between the IL-13 gene polymorphisms and susceptibility of asthma." (PMID 23437086, 2013). "This meta-analysis suggested that the IL13 -1112C/T and +2044A/G polymorphisms were risk factors for asthma." (PMID 23437086, 2013). "More studies with African American population are needed to evaluate the effect of IL-13 +1923C/T polymorphism on asthma risk." (PMID 23841068, 2013). "This was, to our knowledge, the most comprehensive meta-analysis of the association between IL-13 polymorphisms and asthma susceptibility." (PMID 23437086, 2013). "In severe asthma, monoclonal antibody to IL-13 use is associated with improvement in lung function in humans and airway hyper-responsiveness in a murine model." (PMID 24314122, 2013).